H2AC8 (H2A clustered histone 8)
Description:
Core component of nucleosome. Nucleosomes wrap and compact DNA into chromatin, limiting DNA accessibility to the cellular machineries which require DNA as a template. Histones thereby play a central role in transcription regulation, DNA repair, DNA replication and chromosomal stability. DNA accessibility is regulated via a complex set of post-translational modifications of histones, also called histone code, and nucleosome remodeling.
Synonyms: H2AFA; HIST1H2AE; H2A/a; H2A.1; H2A.2
Tractability: Small molecule: a structure with a bound ligand is known. PROTAC: UniProt records ubiquitination sites on it; ubiquitination databases record sites on it.
Gene: Protein-coding gene on chromosome 6 (26,216,921 to 26,218,515, forward strand). Ensembl gene ENSG00000277075.
Subcellular location: Nucleus; Chromosome
Subcellular location (Human Protein Atlas): Nucleoplasm
Pathways (Reactome):
Gene expression (Transcription): B-WICH complex positively regulates rRNA expression; DNA methylation; ERCC6 (CSB) and EHMT2 (G9a) positively regulate rRNA expression; MLL4 and MLL3 complexes regulate expression of PPARG target genes in adipogenesis and hepatic steatosis; NoRC negatively regulates rRNA expression; PRC2 methylates histones and DNA; RNA Polymerase I Promoter Escape; RNA Polymerase I Promoter Opening; RUNX1 regulates genes involved in megakaryocyte differentiation and platelet function; RUNX1 regulates transcription of genes involved in differentiation of HSCs; Regulation of endogenous retroelements by KRAB-ZFP proteins; Regulation of endogenous retroelements by Piwi-interacting RNAs (piRNAs); Regulation of endogenous retroelements by the Human Silencing Hub (HUSH) complex; SIRT1 negatively regulates rRNA expression; Transcriptional regulation by small RNAs
Chromatin organization: CHD1 and CHD2 subfamily; CHD6, CHD7, CHD8, CHD9 subfamily; ChAHP complex assembly; HATs acetylate histones; HDACs deacetylate histones; Interaction of NuRD complexes with transcription factors; NuRD complex assembly; RMTs methylate histone arginines
Cell Cycle: Condensation of Prophase Chromosomes; Deposition of new CENPA-containing nucleosomes at the centromere; Inhibition of DNA recombination at telomere; Packaging Of Telomere Ends
DNA Repair: Cleavage of the damaged purine; Cleavage of the damaged pyrimidine; Recognition and association of DNA glycosylase with site containing an affected purine; Recognition and association of DNA glycosylase with site containing an affected pyrimidine
Disease: Defective pyroptosis; Dengue Virus-Host Interactions; HCMV Early Events; HCMV Late Events
Metabolism of proteins: Amyloid fiber formation; Metalloprotease DUBs; UCH proteinases; Ub-specific processing proteases
Signal Transduction: Activated PKN1 stimulates transcription of AR (androgen receptor) regulated genes KLK2 and KLK3
and 15 more pathways
Gene Ontology:
Molecular function: protein binding; structural constituent of chromatin; DNA binding; protein heterodimerization activity
Biological process: negative regulation of cell population proliferation; chromatin organization; heterochromatin formation; protein localization to CENP-A containing chromatin
Cellular component: CENP-A containing nucleosome; extracellular exosome; nucleoplasm; nucleosome; nucleus; chromosome
Genetic constraint (gnomAD): Loss-of-function variants: 9 observed, 6.64 expected, observed/expected ratio (o/e) 1.36, 90% interval 0.79 to 1.9. That is too few expected variants to judge how well the gene tolerates losing a copy. Missense variants: 141 observed, 192.25 expected, observed/expected ratio (o/e) 0.73, 90% interval 0.64 to 0.84. Synonymous variants: 176 observed, 87.1 expected, observed/expected ratio (o/e) 2.02.
Homologues: Orthologues: chimpanzee H2AC8 (100% identical), mouse H2ac7 (100% identical), pig H2AC8 (100% identical), rabbit H2AC7 (100% identical), rat Hist1h2ac (100% identical), Drosophila melanogaster His2A:CG31618 (85% identical), Drosophila melanogaster His2A:CG33808 (85% identical), Drosophila melanogaster His2A:CG33814 (85% identical), Drosophila melanogaster His2A:CG33817 (85% identical), Drosophila melanogaster His2A:CG33820 (85% identical), Drosophila melanogaster His2A:CG33823 (85% identical), Drosophila melanogaster His2A:CG33826 (85% identical), and 13 more. Paralogues in human: H2AC4 (100% identical), H2AC25 (99% identical), H2AC7 (99% identical), H2AC11 (98% identical), H2AC13 (98% identical), H2AC15 (98% identical), H2AC16 (98% identical), H2AC17 (98% identical), H2AC6 (98% identical), H2AC12 (97% identical), H2AC18 (97% identical), H2AC19 (97% identical), and 15 more.
Diseases named in the same sentence as H2AC8 in open-access papers:
H2AC8 is named in the same sentence as 5 diseases in open-access papers, as found by Europe PMC text mining. Sharing a sentence is not in itself a finding about the gene and the disease.
H2AC8 shares sentences with these, for which no sentence is quoted: Alcoholism (1 paper); infection (1); pancreatic cancer (1); systemic lupus erythematosus (1); viral infections (1).